SORT1 (sortilin 1)
Diseases named in the same sentence as SORT1 in open-access papers (continued):
Sharing a sentence is not in itself a finding about the gene and the disease.
ovarian carcinoma (8 papers, 2021 to 2024). A malignant neoplasm originating from the surface ovarian epithelium. "SORT1 expression was assessed in many ovarian carcinoma cell lines, including SKOV3, using Western blotting." (PMID 39519199, 2024). "Studies in breast and ovarian cancer cell lines have shown that TH1902 exploited SORT1’s ligand internalization functions and exerted potent antiproliferative and anti-migratory effects." (PMID 35454785, 2022). "In the current study, high levels of SORT1 expression were confirmed in ovarian cancer tissues and ovarian cancer-derived cell lines, and these findings were further extended to endometrial cancer tissues and respective cell lines." (PMID 35454785, 2022). "IHC scoring was also performed with regard to ovarian cancer subtypes and compared to the very low levels of SORT1 found in healthy tissues." (PMID 35454785, 2022). "Overall, these data confirm the cytotoxic activity of TH1902 against ES-2 and SKOV3 ovarian cancer cells, just as was previously shown against the SORT1-expressing TNBC cell line MDA-MB-231." (PMID 35454785, 2022). "In this study, sortilin (SORT1) receptor was detected in in vitro 3D capillary-like structures formed by ES-2 ovarian cancer and MDA-MB-231 TNBC-derived cells when grown on Matrigel." (PMID 34751242, 2021). "Further research into the ectopic expression of SORT1 in ovarian carcinoma has shown a four-fold increase in its gene expression in carcinoma tissues compared to non-malignant tissues, highlighting its absence in normal ovarian tissue and its potential as a novel tumor marker." (PMID 39033780, 2024). "Similarly to breast and ovarian cancer, high SORT1 expression was assessed in endometrial cancer cell lines (HEC-1-A, HEC-1-B, AN3-CA, SK-UT-1B, and KLE cell lines) using Western blot." (PMID 39519199, 2024). "Fortuitously, SORT1 is being explored as a target for ovarian cancer." (PMID 39160301, 2024). "In a previous study, SORT1 was reported to have a role in vasculogenic mimicry (VM), and TH1902 was shown to inhibit in vitro VM in these cells and in the ES-2 ovarian cancer cell line." (PMID 35454785, 2022). "In vitro, TH1902 inhibited cell proliferation and triggered higher SORT1-dependent cell apoptosis than unconjugated docetaxel did in ES-2 and SKOV3 ovarian cancer cell lines." (PMID 35454785, 2022). "For instance, CircRAB11FIP1 promotes ovarian cancer via miR‐129/DSC1 axis (Zhang, Zhu, & Hu, 2021), circEPSTI1 upregulates SLC7A11 expression in cervical cancer by miR‐375 and circ_0110389 accelerates gastric cancer through miR‐127‐5p/SORT1." (PMID 39632246, 2024). "These new findings also indicate that both peptide-drug conjugates, in addition to their reported cytotoxicity, could possibly inhibit VM in SORT1-positive TNBC and ovarian cancer patients." (PMID 34751242, 2021). "Interestingly, a heterodimerization between NTR1 and SORT1, leading to NT internalization, has been described in colonic adenocarcinoma cell lines, making NT/NTR1/SORT1 a potential therapeutic target for ovarian carcinoma." (PMID 39519199, 2024). "Similarly, ovarian cancer studies reveal variable NTR1 expression between different cell lines and SORT1 expression in many cancer cell lines, with significant overexpression in malignant tissues compared to nonmalignant ones concerning both NTR1 and SORT1 expression." (PMID 39519199, 2024).
glioblastoma (5 papers, 2014 to 2025). The most malignant astrocytic tumor (WHO grade IV). "This assertion is further substantiated by previous investigations that correlate elevated SORT1 levels with poor prognostic outcomes in liver cancer and glioblastoma." (PMID 40781926, 2025). "A previous study also reported that SORT1 promotes tumor metastasis via Wnt/β-catenin in glioblastoma." (PMID 40750784, 2025). "Recently, SORT1 has also been found in different types of human cancer cells and tissues, including breast, pancreatic cancer, lymphocytic leukemia, and glioblastoma, which suggests a role for this protein in tumorigenesis and progression." (PMID 40750784, 2025). "We treated U251 human glioblastoma cells, which have the inherent capacity to release PGRN, with the anti-SORT1 antibody." (PMID 33384578, 2020).
hepatocellular carcinoma (5 papers, 2020 to 2025). A malignant tumor that arises from hepatocytes. "The coexpression network of Sort1 in the hepatocellular carcinoma (HCC) group was analyzed using LinkedOmics to determine the biological significance of the gene." (PMID 35847356, 2022). "Next, the effects of Sort1 knockdown on the proliferation of hepatoma cells HepG2 were investigated using the CCK-8 assay." (PMID 35847356, 2022). "This study investigates the role of Sort1 in hepatocellular carcinoma (HCC)." (PMID 35847356, 2022). "The Sort1 gene was identified and its expression was then verified by TCGA and HCCDB (a database of hepatocellular carcinoma expression atlas) databases." (PMID 35847356, 2022).
lung adenocarcinoma (5 papers, 2017 to 2025). A carcinoma that arises from the lung and is characterized by the presence of malignant glandular epithelial cells. "It was evident in these data that the SORT1 mRNA expression is highly variable among different human cancers, with both lung adenocarcinomas and SCC displaying loss of expression, while cancers such as liver, ovarian, and pancreatic carcinomas demonstrate overexpression." (PMID 38893272, 2024). "Interestingly, lung adenocarcinomas with EGFR TKI—sensitive mutations expressed high levels of SORT1." (PMID 29084952, 2017). "We utilized immunohistochemistry to evaluate the expression levels of SORT1 in both cancerous tissues and adjacent non‐cancerous tissues obtained from patients diagnosed with lung adenocarcinoma." (PMID 40781926, 2025). "In addition, we also searched the Human Protein Atlas database and found that SORT1 was increased in lung adenocarcinoma." (PMID 40781926, 2025).
Sepsis (5 papers, 2021 to 2024). Sepsis is defined as life-threatening organ dysfunction caused by a dysregulated host response to infection. "Importantly, we identified endothelial cell (CD31+Sele+Glut1+) and neutrophil (Ly6G+Lta4h+Sort1+) subsets that were closely associated with acute liver dysfunction during sepsis progression." (PMID 37122356, 2023). "Using clinical sepsis samples and normal healthy controls, we identified the key genes associated with inflammation in sepsis, including remarkable increases in FKBP5 and SORT1 expression, as indicated through RT-PCR studies." (PMID 33959663, 2021). "Progranulin has an important functional and regulatory role in early sepsis and is part of a molecular network activated during the early antimicrobial response to sepsis with sortilin (SORT1 gene) as an important co-regulator." (PMID 34476621, 2021). "AKT1, top up- (FKBP5, SORT1, VNN1, and CST7) and downregulated (PRR5L, SH2B3, SULF2, PLEKHO1, and PTPN6) genes in sepsis were validated using RT-PCR." (PMID 33959663, 2021). "This network demonstrated an upregulating effect of miR-125b-5p on SORT1 and GRN, and identified vascular endothelial growth factor A (VEGFA) as a possible target of GRN in sepsis." (PMID 34476621, 2021).
colorectal cancer (4 papers, 2016 to 2023). A primary or metastatic malignant neoplasm that affects the colon or rectum. "SORT1 overexpression is associated with poor prognosis in colorectal cancer." (PMID 36091132, 2022). "Several studies have demonstrated that SORT1 expression is elevated in several types of tumors, which is correlated with a poor prognosis, such as liver, gastric, prostate, and colorectal cancers." (PMID 37511958, 2023). "Previous studies have shown that Sort1 acts as an oncogene that is linked with poor prognosis in gastric, prostate, and colorectal cancers, but there is no relevant study on a similar mechanism in HCC." (PMID 35847356, 2022).
depression (4 papers, 2015 to 2022). "The serum sortilin level was investigated in 152 individuals with depression and 216 control individuals, and eight genetic markers located within the SORT1 gene were successfully analysed for association with depression." (PMID 26556286, 2015). "The decrease of depressive-like behavior of Sort1−/− mice may suggest some dysfunctions of the TREK-1 channel for which its blockade or its deletion results in a depression-resistant phenotype." (PMID 30127743, 2018). "Sortilin (SORT1), which is also known as the neurotensin receptor 3 or 95-kDa RAP binding protein (Gp95), is a multitasking protein involved in numerous pathological processes such as cancer development, cardiovascular impairment, metabolic diseases, and depression." (PMID 35454785, 2022). "On another hand, since TREK-1 was described to be a potent target in depression, the aim of the present work was to analyze using electrophysiological, biochemical, and behavioral approaches, the phenotype of Sort1−/− mice regarding antidepressive-like behavior." (PMID 30127743, 2018). "Since the increase of sortilin expression is associated with depression, our results describing a resistance to depression in Sort1−/− mice could be the consequence of the absence of sortilin." (PMID 30127743, 2018).
gastric cancer (4 papers, 2021 to 2024). A primary or metastatic malignant neoplasm involving the stomach. "Additionally, hsa_circ_0110389 has been found to upregulate SORT1 to promote gastric cancer progression by sponging miR-127-5p and miR-136-5p." (PMID 37275878, 2023).
Insulin resistance (4 papers, 2018 to 2024). Increased resistance towards insulin, that is, diminished effectiveness of insulin in reducing blood glucose levels. "Ceacam2-deficient mice develop insulin resistance, and Sort1 is involved in intracellular glucose transport and its expression is downregulated in diabetic mice and humans." (PMID 39360185, 2024). "Similarly to the first Sort1-/- model described, NT-deficient mice are resistant to DIO, hepatic steatosis and insulin resistance." (PMID 30697159, 2018). "Nonetheless, on the contrary, the dexamethasone-mediated insulin resistance is shown to be not accompanied by the reduced gene expression contents of SORT1." (PMID 34784266, 2022). "Paradoxically, studies on Sort1−/− mice have so far not shown any signs of insulin resistance or reduced glucose handling." (PMID 36397124, 2022).
lung carcinoma (4 papers, 2022 to 2025). "Sortilin‐1 (SORT1) has been implicated in the pathogenesis of various malignancies, but its role in non‐small cell lung cancer (NSCLC) remains to be elucidated." (PMID 40781926, 2025). "A previous study utilizing RT‐PCR indicated that SORT1 mRNA levels were decreased in lung cancer tissue." (PMID 40781926, 2025). "In our study, we observed that SORT1 expression was significantly upregulated in lung cancer tumor tissues, a finding that aligns with earlier studies identifying increased SORT1 levels in other cancer types, including breast, ovarian, and liver cancers." (PMID 40781926, 2025). "In contrast, the current study used immunohistochemistry and found that SORT1 was increased in lung cancer tissue." (PMID 40781926, 2025). "A prior study demonstrated that SORT1 plays a critical role in exosome release in lung cancer cells, underscoring its conserved function in vesicular trafficking and exosome secretion." (PMID 40750784, 2025). "Our experimental results indicate that the knockdown of SORT1 reduces the proliferation, migration, and invasiveness of lung cancer cells in vitro, while simultaneously promotes apoptosis." (PMID 40781926, 2025). "A notable strength of our study lies in the identification of miR‐146a as a regulatory factor for SORT1 and its subsequent influence on apoptosis, invasiveness, and proliferation in lung cancer through the modulation of SORT1 expression." (PMID 40781926, 2025). "We determined the mRNA expression of both SORT1 transcript variants (SORT1A and SORT1B) by RT-qPCR in 81 paired lung cancer and histologically normal adjacent tissues." (PMID 38893272, 2024). "However, there remains a relative paucity of research investigating the specific relationship between SORT1 and lung cancer." (PMID 40781926, 2025). "However, SORT1 was considered as an anti-oncogene in lung cancer by inhibiting the EGFR signaling pathway." (PMID 40750784, 2025). "Furthermore, the influence of SORT1 on apoptosis, migration, and invasiveness in lung cancer, as well as the miRNAs that regulate SORT1, has yet to be comprehensively examined." (PMID 40781926, 2025). "Our findings provide solid support for the involvement of abnormal SORT1 regulation in lung cancer pathogenesis and enables the generation of strong hypotheses, opening up multiple avenues for future functional analysis of the gene." (PMID 38893272, 2024).
pancreatic cancer (4 papers, 2011 to 2024). "We clearly demonstrated that highly malignant pancreatic cancer cells express NTSR1, not NTSR2 and SORT1, as a receptor for NTS." (PMID 33034134, 2021).
type 2 diabetes (4 papers, 2016 to 2025). "Moreover, FURIN, ASGR1, SORT1, TFPI, PGF, F2R, and EFNA1 were also associated with SBP, adiposity, and type 2 diabetes." (PMID 37940228, 2023).
autism (3 papers, 2019 to 2025). Persistent deficits in social interaction and communication and interaction as well as a markedly restricted repertoire of activity and interest as well as repetitive patterns of behavior. "Notably, suppressing SORT1 expression amplified PGRN levels, lessened microglial activation, and mitigated inflammation, thereby alleviating autism‐like behaviors." (PMID 39218796, 2024).
endometrial tumors (3 papers, 2022 to 2024). "Here, high expression of SORT1 was found in >75% of the clinically annotated ovarian and endometrial tumors analyzed by immunohistochemistry." (PMID 35454785, 2022). "Sortilin (SORT1) is a multifunctional protein whose expression levels have been documented in multiple malignancies, such as ovarian and endometrial tumors." (PMID 35454785, 2022). "SORT1 is highly expressed in various cancers, including ovarian and endometrial tumors." (PMID 39033780, 2024). "Since SORT1 is expressed in ovarian and endometrial tumors as well as in cell lines derived from these tumors, and since SORT1 binds and internalizes the TH19P01 peptide, it was next investigated whether TH1902 could be used to treat such tumors." (PMID 35454785, 2022). "Increased SORT1 staining was also seen in endometrial tumors compared to normal endometrial tissues, as 10 out of 12 (83%) samples showed higher expression levels of SORT1 than in healthy tissues." (PMID 39519199, 2024).
liver cancer (3 papers, 2021 to 2023). An epithelial or non-epithelial malignant neoplasm that arises from the liver. "SORT1 has been shown to promote the proliferation and migration of liver cancer cells by regulating immune cell infiltration." (PMID 37205113, 2023). "Sort1 expression was also related to survival outcomes of the HCC cohort based on the Kaplan–Meier plotter's liver cancer RNA-seq database and plotted Kaplan–Meier survival curves as in this case." (PMID 35847356, 2022). "By analyzing Sort1 expression based on multiple databases and bioinformatics analyses, it was observed that most cancers, including liver cancer, abnormally expressed this gene." (PMID 35847356, 2022). "It was found that Sort1 expression was higher in liver cancer cell lines (Huh7, HepG2, Hep3B, LO2, and MHCC97H) than that on normal human hepatocytes (THLE-2), with the highest expression level occurring in HepG2 cells." (PMID 35847356, 2022).
acne (2 papers, 2024). An inflammatory process of the sebaceous glands which is characterized by comedones, nodules, papules and/or pustules on the skin. "Furthermore, SORT1 was found to colocalize with GRN in acne lesions." (PMID 38854033, 2024).
asthma (2 papers, 2017 to 2025).
B-cell chronic lymphocytic leukemia (2 papers, 2019 to 2025). "In another study, a significant expression of SORT1 on the surface of PBMCs in chronic lymphocytic leukemia patients." (PMID 40750784, 2025).
calcification (2 papers, 2022 to 2024). Process by which organic tissue becomes hardened by the physiologic deposit of calcium salts. "The expression of SORT1 in cardiomyocytes is consistent with its pathological role in valvular calcification, although its lower expression in vascular smooth muscles contradicts its reported role in arterial calcification." (PMID 38255751, 2024). "The expression of SORT1 is highly enriched in adipocytes and smooth muscle cells, which, together with its contribution to tissue fibrosis and calcification, makes it a vital target in the development of unstable atherosclerotic plaques (UAPs) and vascular calcification." (PMID 38255751, 2024).
chronic kidney disease (2 papers, 2023 to 2024). Impairment of the renal function secondary to chronic kidney damage persisting for three or more months. "Key genes involved in lipid metabolism and vascular calcification, such as SORT1 and PCSK9, are linked to both coronary atherosclerosis and systemic conditions like chronic kidney disease (CKD) and osteoporosis." (PMID 39518317, 2024).
Cognitive impairment (2 papers, 2022 to 2025). Abnormal cognition is characterized by deficits in thinking, reasoning, or remembering. "Furthermore, several human investigations have found disparate single nucleotide polymorphisms of the SORT1 (sortilin 1) gene; for example, rs17646665 lowers AD risk, while rs1010159 appears to increase the risk of mild cognitive impairment (MCI) progressing to AD." (PMID 35111364, 2022).
Crohn disease (2 papers, 2020 to 2022). A gastrointestinal disorder characterized by chronic inflammation involving all layers of the intestinal wall, noncaseating granulomas affecting the intestinal wall and regional lymph nodes, and transmural fibrosis. "These “bystander” effects reflect their shared regulatory architecture with known causal genes, and our observations around met-QTLs mirror recent findings at the SORT1 and NOD2 loci (associated with LDL cholesterol and Crohn’s disease, respectively)." (PMID 31978332, 2020).